CDKN2B (cyclin dependent kinase inhibitor 2B)
Diseases named in the same sentence as CDKN2B in open-access papers (continued):
Sharing a sentence is not in itself a finding about the gene and the disease.
tumor (continued). "This is one possible explanation for the short response in our patient who has co‐mutations identified in the initial tumour sample at diagnosis including NTRK1 over‐expression, TERT gain of function mutation and CDKN2A and CDKN2B loss." (PMID 39188081, 2024). "Exposure to Eo33-EV, but not to Eo5-EV, up-regulated cyclin-dependent kinase inhibitor (CDKI) protein-related genes in tumor cells, specifically Cdkn1b and Cdkn2b in B16 cells and Cdkn2b and Cdkn1a in TC1 cells." (PMID 39061080, 2024). "The IHC study of c-MYC and CDKN2B in canine TVTs found that most of the staining was focal and confined to the cytoplasm of tumor cells (Figure-3a)." (PMID 39185058, 2024). "An astrocytoma, IDH mutant with WHO grade 4 is characterized by the presence of homozygous deletions of the tumor suppressor genes for CDKN2A or CDKN2B and/or microvascular proliferation and/or the presence of tumor necrosis." (PMID 36941392, 2023). "We also examined the expression levels of RB1 and CDKN2B in tumor specimens from five patients with PR and PD using immunohistochemical staining." (PMID 37781033, 2023). "Our studies conclude that YTHDF2 is capable of regulating neoplastic transformation and cell proliferation among astrocytes by degrading tumor suppressor transcripts including CDKN2B." (PMID 36973285, 2023). "CDKN1A and CDKN2B exert an important tumor-suppressive function by regulating cell cycle progression." (PMID 37932451, 2023). "Whilst the tumor suppressor’s p14ARF and p16INK4A are proven to be encoded by CDKN2A, the p15INK4B protein is encoded using CDKN2B." (PMID 37845622, 2023). "Aberrant YTHDF2 upregulation markedly hampers expression of multiple m6A-marked tumor-suppressing transcripts, including CDKN2B and SPOCK2, and induces oncogenic reprogramming." (PMID 36973285, 2023). "Two important tumor suppression genes, CDKN2A, and CDKN2B, are transcribed from 9p21.3, the deletion of which contributes to tumorigenesis and tumor development, including GC." (PMID 37319315, 2023). "For example, recurrent amplification of oncogenes such as MYC, ERBB2 (HER2), and FGFR1, and significant loss of tumor suppressors such as CDKN2A and CDKN2B were observed in the high-CRRS group." (PMID 36936912, 2023). "In our cohort, after adjusting for patient characteristics, treatments, and other tumor genetic alterations, we observed that while CDKN2A and CDKN2B deletions were associated with worse survival, EGFR amplification was not correlated with poor outcomes." (PMID 36380219, 2022). "The simultaneous deletions of CDKN2A and CDKN2B is frequently identified across many tumour types as a consequence of homozygous 9p21.3 deletions involving the CDKN2A/p14ARF/CDKN2B loci." (PMID 35324914, 2022). "CDKN2B encodes for cyclin-dependent kinase 6 (CDK6), which regulates the cell cycle; its mutation in the cancer setting is associated with uncontrolled tumor growth." (PMID 35159000, 2022). "Of the four putative tumor suppressors, CSMD3 has a disputed cancer role and a likely inflated mutation rate, while CDKN2B cooperates with its paralog CDKN2A to inhibit cell cycle, supporting its tumor suppressor role." (PMID 35078504, 2022). "The tumor suppressor genes CDKN2A and CDKN2B, which encode the cell cycle proteins p16, p14ARF and p15, are located in the 9p21.3 region, and are frequently lost in MF in tumor stages or in transformation, and are associated with a poor prognosis." (PMID 36291756, 2022).
tumor (continued). "p16INK4A and p15INK4B, encoded by CDKN2A and CDKN2B, respectively, play significant roles as tumor suppressors in the INK4 family." (PMID 35892870, 2022). "The potency of CDKN2B/p15INK4B in tumor suppression relies on its strong binding via key N-terminal residues to and inhibition of CDK4/CDK6." (PMID 33824349, 2021). "The skin metastasis sample showed a very similar pattern of alterations in driver genes as compared with the treated tumor, including the PIK3CA hotspot mutation, the amplifications in CCND1, EGFR, and FGFR3, and the deletions in CDK1B, CDKN2A, and CDKN2B." (PMID 34680239, 2021). "The treated tumor showed several CNVs in driver genes, including amplifications in MCL1, TERT, CCND1, AKT1, MYC, EGFR, and FGFR3; deletions in CDK1B, CDKN2A and CDKN2B; a PIK3CA hotspot mutation; and a high TMB." (PMID 34680239, 2021). "The majority of CRC biopsies displayed PRMT5- and CDKN2B-positive staining in both cytoplasmic and nuclei of tumor cells, whereas EZH2 was apparently expressed in the nuclei of tumor cells." (PMID 33664859, 2021). "CDKN2B encode the p15Ink4b protein that interacts with CDK4/6 and inhibits its activation by cyclin D and thus acts as a tumor suppressor." (PMID 34249754, 2021). "Nevertheless, low CDKN2B expression was correlated with poor overall survival (P < 0.01), implying a role as tumor suppressor in CRC." (PMID 33664859, 2021). "Conversely, loss of the endogenous CDK4/6 inhibitors (CDKN2A, CDKN2B, CDKN2C, and CDKN2D) or RB-family (RB1, RBL2, and RBL1) are also observed in specific tumor settings, in total the RB-pathway is subject to genetic perturbation in greater than 30% of tumors." (PMID 32242058, 2020). "Chromosome 9p contains numerous tumor-associated genes, such as PAX5 at 9p13.2, CDKN2A, CDKN2B, MTAP, IFN, MLLT3, PTPLAD2 at 9p21.3, and JAK2 at 9p24.1." (PMID 31168295, 2019). "For the CNVs of CDKN2A and CDKN2B in tumor tissue, we found that CDKN2A or CDKN2B loss was detected in 27% (44/161) of the ESCC samples." (PMID 31700061, 2019). "NFAT-dependent repression of tumor failsafe programs in PDAC has been previously reported in the context of transcriptional inactivation of the tumor-suppressor gene Cdkn2b, which negatively controls cell cycle progression and induces cellular senescence." (PMID 31171768, 2019). "Mutational profiling was carried out by targeted deep sequencing and showed that his tumor tissue harbored CDKN2A and CDKN2B loss." (PMID 31700061, 2019). "The CDKN2B/p15 gene plays a critical role in cell cycle progression and is considered to be a target for tumor inactivation in Nbl cells." (PMID 29435113, 2018). "Since the expression level of CDKN2A and CDKN2B are critical to tumorigenesis, we believe the CN losses of these two genes contribute to the malignancy of the tumor." (PMID 30567531, 2018). "Knockdown of members of this Polycomb group complex led to increased expression of the CDKN2A and CDKN2B tumor suppressors in the Chr9p21 locus." (PMID 30460243, 2018). "The CDKN2B gene lies adjacent to the tumor suppressor gene CDKN2A in a genomic region that is frequently mutated and/or deleted in various tumor types." (PMID 29343775, 2018). "For example, the lncRNA called ANRIL (antisense noncoding RNA in the INK4 locus) is a tumor suppressor which is transcribed in the antisense direction of Cyclin Dependent Kinase Inhibitor 2B (CDKN2B)." (PMID 28210622, 2017). "Genomic profiling revealed that he harbors a heterozygous deletion in the germline of chromosome 9p21.3 encompassing the CDKN2A and CDKN2B tumor suppressor genes." (PMID 28699883, 2017).
tumor (continued). "CDKN2B knockdown using siRNA weakened the effect of ADM+VER, indicating that ADM+VER promotes HCC cell apoptosis and that CDKN2B genes participate in VER-mediated promotion in tumor cell apoptosis." (PMID 29299129, 2017). "We studied the promoter regions of two genes that play important tumour suppressor roles in cancer, CDKN2B and DAPK1." (PMID 28392841, 2017). "The most well-studied TSG targets of PcGs are the CDKN2A and CDKN2B loci encoding p14 (ARF), p15 (INK4B) and p16 (INK4A), whose products participate in major tumour suppressor networks that are disabled in human cancer." (PMID 28758948, 2017). "Activation of the Wnt pathway induces therefore an increased expression of negative regulators of the cell cycle such as the tumour suppressors Cdkn2a (p16Ink4a, p19Arf) and Cdkn2b (p15Ink4b)." (PMID 28346462, 2017). "Our results showed that after 1 week of MycN knockdown, there was significant increase in the expression of well-recognized tumor suppressors that induce G1 cell cycle arrest, such as Cdkn1a, Cdkn2a and Cdkn2b." (PMID 26815535, 2016). "CDKN2B, known as a tumor suppressor, participates in cell cycle regulation via retinoblastoma (Rb) pathway." (PMID 27905995, 2016). "Tumour suppressor genes CDKN2A (encoding p16INK4a), ARF (encoding p14ARF), and CDKN2B (encoding p15INK4b) residing on chromosome 9p21 are all associated with the anaplastic grade." (PMID 27429002, 2016). "Consistently, we have illustrated that MycN knockdown in human NCSCs increased the expression of Cdkn1a, Cdkn2a and Cdkn2b, emphasizing the critical role of these tumor suppressors in stem cell growth and cell cycle progression." (PMID 26815535, 2016). "And we know, TGF-β/Smad3 signaling has been regarded as tumor suppressor during tumor progression since TGF-β-induced CDKN1A (P16) and CDKN2B (P15) expression is correlated with tumor inhibition." (PMID 24427302, 2014). "CDKN2B is located adjacent to tumor suppressor CDKN2A in the chromosome 9, which is frequently mutated and deleted in a wide variety of neoplasms." (PMID 24098334, 2013). "CDKN2A/ARF and CDKN2B are three tumour suppressor genes which play a central role in cell cycle inhibition, senescence and stress-induced apoptosis." (PMID 23101500, 2012). "ANRIL directly binds to the SUZ12 protein, an essential component of polycomb repressive complex 2, and is required for SUZ12 occupancy of the CDKN2A/CDKN2B tumour suppressor genes as well as for their epigenetic silencing." (PMID 23101500, 2012). "Two important tumor suppressor loci map 9p21: CDKN2B (p15INK4B) and CDKN2A, which code for two alternative protein products, p14ARF and p16INK4A." (PMID 22389839, 2012). "The losses encompassed the tumor suppressor genes CDKN2A and CDKN2B, which are frequently deleted in many tumor types." (PMID 22613809, 2011). "DBC1 and CDKN2B have been shown to have tumor-suppressor activity through the negative regulation of G1 cell cycle progression, and their loss of function has been associated with an advantage in proliferation, growth, and malignant transformation." (PMID 20808941, 2010). "Although we were able to confirm decreased CDKN2B expression in the tumour, we were unable to confirm this in the earlier staged cases in the validation panel." (PMID 18248679, 2008). "Current evidence shows that although these two members of INK4 family have significantly overlapping roles, there are p15INK4b-unique tumor suppressing function that are illustrated by more aggressive tumors with CDKN2B deletion especially in certain signaling context (e.g. oncogenic RAS)." (PMID 38561743, 2024). "Mice lacking two Ink4 genes, such as Cdkn2a/Cdkn2b or Cdkn2a/Cdkn2d, display increased tumor susceptibility compared to p16INK4a-null mice." (PMID 38561743, 2024). "Case 13, a 78 year-old man with GBM, +7/−10 and ATM mutation were found in the CSF ctDNA but not in the tumor DNA, at the same time, loss of CDKN2B was only found in tumor DNA." (PMID 37822669, 2023).
tumor (continued). "To understand the tumor cell-autonomous mechanism underlying the tumor-promoting function of SMIMP and SMC1A, we further investigated the two targets cyclin-dependent kinase inhibitor (CDKN)1A and CDKN2B that have an established role in cell proliferation." (PMID 37932451, 2023). "However, CDKN2B, also known as p15, is another critical tumor suppressor, which inhibits cyclin kinases CDK4 and CDK6." (PMID 36952446, 2023). "Together, these data revealed common features of GBM, including gain of chr.7 and loss of chr.10, lacking IDH1/2 mutations, high frequency of TERT promoter mutation, loss of critical tumor suppressors (e.g., PTEN and CDKN2A/CDKN2B), high frequency of PDGFA and EGFR amplification." (PMID 34987659, 2022). "Losses of PTEN and CDKN2A/CDKN2B 7, 20 were frequent events in 7 and 8 tumor foci, respectively." (PMID 34987659, 2022). "The closest protein-coding gene to this SNP is CDKN2B (cyclin dependent kinase inhibitor 2B) which is adjacent to the tumor suppressor gene CDKN2A (Cyclin-Dependent Kinase 4 Inhibitor A) in a region that is frequently mutated and deleted in a wide variety of tumors." (PMID 35884374, 2022). "Furthermore, PRMT5, EZH2 and CDKN2B protein expression levels in CRC samples (80 tumor and 80 normal tissues) were analyzed by IHC staining." (PMID 33664859, 2021). "Moreover, another study demonstrated an average CDKN2B hypomethylation of 6.8% in 47% of the patients with azacitidine, which corroborated with the suppression of CDKN2B and tumor growth in SKM-1 cell lines in vitro." (PMID 34358067, 2021). "Finally, two tumor suppressors, CDKN2B and TSLC1, were upregulated upon MCM3 knockdown in TamR cells." (PMID 33398005, 2021). "While loss of p16INK4a was initially believed to be the main target during cancer progression, the discovery of p14ARF and prevalence of large deletions or silencing of the locus spanning INK4a, ARF and CDKN2B have highlighted the importance of these other tumor suppressors." (PMID 32344731, 2020). "Meanwhile, a deletion peak of CDKN2A and CDKN2B was also observed in these tumours." (PMID 33006444, 2020). "For instance, ANRIL and P21-AS lncRNAs are located near critical tumor suppressor genes CDKN2B and CDKN1A, respectively, and knockdown of these NATs could be a potential therapy to inhibit tumor growth in multiple malignancies." (PMID 32854207, 2020). "Notably, we did not observe the direct association of TET3 with these factors, and found that several tumor suppressor genes (CDKN2B, ZIC2, and miR-196a) and oncogenes (PAX2, IL2RA, SOX11, and PAK7) were associated with TET3 in AML biology." (PMID 32209730, 2020). "Based on genetic linkage analyses, the Cdkn2ab gene was proposed as the critical component of the tumour suppressor R locus (so named due to 55% amino acid homology with the human tumour suppressor genes CDKN2A and CDKN2B that are frequently mutated in melanoma)." (PMID 32652526, 2020). "Silencing of Cdkn2b is indispensable for Rb1 phosphorylation and tumor induction." (PMID 30910991, 2019). "EZH2 was found to be overexpressed in MDS tumor cells associated with methylation of tumor suppressor gene cyclin dependent kinase inhibitor 2B (p15INK4B) compared with tumor cells that p15INK4B is not methylated." (PMID 31886200, 2019). "It was concluded that ANRIL's function may be, at least in part, to repress the CDKN2A and CDKN2B tumor suppressors." (PMID 30460243, 2018). "Cyclin-dependent kinase inhibitor 2B (CDKN2B) is a tumor suppressor." (PMID 28978151, 2017). "These might include genes with tumor suppressive properties, such as CDKN2B (9p21), SH3GL2 (9p22), PTPRD (9p23), and DOCK8 (9p24)." (PMID 27835607, 2016).
tumor (continued). "One tumor suppressor gene is CDKN2B (cyclin-dependent kinase inhibitor 2B), which encodes p15INK4B." (PMID 26634163, 2015). "Targeted sequencing of the primary tumor revealed deletions of CDKN2A and CDKN2B, a nonsense mutation in ARID2, and single missense mutations of unknown significance in nine other genes." (PMID 26634163, 2015). "CDKN2B also acts as a tumor suppressor in other cancer types." (PMID 24618291, 2014). "According to previous studies, CDKN2B may act as a tumor suppressor gene and a potential effector of TGFβ-induced cell-cycle arrest." (PMID 24098334, 2013). "Both CDKN2A and CDKN2B function as cell cycle regulators and tumor suppressors." (PMID 24330828, 2013). "The loss of one SUZ12 allele in patients with germline NF1 microdeletions may well influence ANRIL-mediated expression regulation of the CDKN2A/CDKN2B tumour suppressor genes." (PMID 23101500, 2012). "Loss of CDKN2B and gain of BCL6, FGF3, and PTP4A3 predicted tumor." (PMID 22570652, 2012). "That reduced gene dosage impacting on CDKN2B also correlates with poor histological characteristics is supportive of the view that it too may play a role in tumor suppression in melanocytes." (PMID 20140953, 2010). "CDKN2B was co-deleted in three (33%) cell lines and two (5%) tumours." (PMID 17533400, 2007). "However, samples equipped with CDKN2A mutation presented no CDKN2B mutation, indicating the independency between the mutation pattern of these two tumor suppressor genes." (PMID 39844467, 2025). "Hence, the downregulation of the CCNA2–CDK2 complex and the overexpression of CDKN2B produced by Ocoxin could have mediated not only the gathering of the cells in the S phase of the cycle but also the induction of tumor cells to an apoptotic stage." (PMID 37299500, 2023). "Besides, we observed the deletion peaks of tumor suppressive genes such as CDKN2A/CDKN2B and PTEN." (PMID 33658560, 2021). "Single deletion of Cdkn2b (codes for p15Ink4b) in mice does not result in any significant tumor susceptibility, while Cdkn2a (codes for p16Ink4a and p19ARF) global knockout animals reach adulthood without any major developmental defects, but begin to spontaneously form tumors at 20 weeks of age." (PMID 33078209, 2021). "In addition to these reported target genes, our findings prove that CDKN2B is another tumor suppressor gene that could be suppressed by multiple mature miRNAs derived from miR-17-92 cluster." (PMID 29752469, 2018). "Even though the microsatellite study pointed to loss of heterozygosity rather than complete loss of the region containing CDKN2A and CDKN2B, no PCR products could be obtained from the tumour for the genes themselves, except for CDKN2A exon 1β." (PMID 19643034, 2009). "None of the tumours retaining alleles of CDKN2B showed mutations of this gene." (PMID 9000591, 1997). "Two major tumor-suppressor genes, cyclin-dependent kinase inhibitor 2A and 2B (CDKN2A and CDKN2B), as well as a large non-coding RNA ANRIL, are often co-deleted in the core region." (PMID 40046620, 2025). "This boundary is adjacent to the TADs containing the cancer genes CDKN2A, CDKN2B, and MTAP, all of which are tumor suppressors, and this boundary is located within a fragile site region (FRA9C)." (PMID 38758740, 2024). "Among these genes, CDKN2A, CDKN2B, CUX1, LRP1B and PTPRD were retrieved as tumor suppressors from the TSGene database." (PMID 38831459, 2024). "In our case, the tumor specimen presented heterozygous deletions of CDKN2A, CDKN2B and CDKN2C, and gains of CDK6 and CCND2." (PMID 38369555, 2024).